SOX2 (SRY-box transcription factor 2)
Diseases named in the same sentence as SOX2 in open-access papers (continued):
Sharing a sentence is not in itself a finding about the gene and the disease.
tumor (continued). "Previous work in our laboratory demonstrated that elevating SOX2 in vivo with an inducible promoter inhibited the tumor growth of PDAC cells (i-SOX2-T3M4) engineered for elevation of SOX2." (PMID 32998722, 2020). "Design and development of drugs targeting SOX2 can provide better therapeutic regimens because SOX2+ tumor cells are key player in seeding CSC and driving therapy resistance." (PMID 30517668, 2020). "The pejorative prognostic value of Sox2 was confirmed by multivariate survival analysis (HR = 1.48, 95% CI 1.02–2.15, p = 0.0420), with tumor size, ER and AR as the covariates (p < 0.0001, Cox proportional-hazard regression)." (PMID 33553286, 2020). "The results of the limiting dilution experiment in vivo showed that overexpression of VDR significantly inhibited tumor occurrence, whereas overexpression of SOX2 attenuated the repressive effect of VDR overexpression." (PMID 32900990, 2020). "Consistently, the percentage of SRY-box transcription factor 2 (SOX2)+ cell population assumed to be responsible for the spread of the tumor was also lower." (PMID 32784599, 2020). "QRT-PCR and IHC analysis showed that SOX2OT depletion significantly decreased ALKBH5 and SOX2 expression level in resected tumor tissues upon TMZ treatment in comparison with the U87TR-sh-NC group." (PMID 32439916, 2020). "SIX1 overexpression was accompanied by an increase in SOX2 levels and activity and the induction of a de-differentiated tumor phenotype." (PMID 32478091, 2020). "The studies described in this report provide new insights into the function of SOX2 in a diverse set of human tumor cells." (PMID 32998722, 2020). "e.g. miR126-3P suppresses SOX2 expressions in GBM patients sensitizing tumor cells to temozolomide (TMZ) treatment." (PMID 32092088, 2020). "As assessed by colony formation and CCK8 assay, we found SOX2 OE or KD had mild effect on colony formation and tumor growth." (PMID 33158915, 2020). "On the other hand, SOX2 overexpression suppresses tumor formation in K-RasG12D-expressing AT2 cells." (PMID 32728033, 2020). "In our tumour cohort, SOX2 RNA-expression was about 2× lower in MES compared to other subtypes, but still remained at a very high level, about 3× higher than in normal brain." (PMID 33339831, 2020). "SOX4 has been characterized as a master regulator of EMT, notably by upregulating SOX2, a well-known mediator of tumour initiation and cancer stem cell maintenance." (PMID 32586280, 2020). "Our findings indicate that elevating SOX2 above endogenous levels in a diverse set of tumor cell types leads to growth inhibition both in vitro and in vivo." (PMID 32998722, 2020). "One patient (St23784/17) had amplifications in the 3q, 6q, 8q, 9q, and 10q22.1 regions of stemness gene localization in her tumor (the following genes were amplified: SOX2, MYC, KLF4, NOTCH1, NODAL)." (PMID 32523653, 2020). "For this purpose, we engineered four additional tumor cell lines for the inducible elevation of SOX2." (PMID 32998722, 2020). "The finding that elevating SOX2 inhibits the proliferation of tumor cells parallels the effects of elevated levels of SOX2 in normal cells." (PMID 32998722, 2020). "Similar to the early tumors and the PDX‐GBMs, ASCL1, OLIG2, and SOX2 were coexpressed in the tumor cells of these terminal tumors, and many ASCL1+ tumor cells were also Ki67+." (PMID 32573857, 2020). "To understand how elevated levels of SOX2 restrict the proliferation of tumor cells, we engineered diverse types of tumor cells for inducible overexpression of SOX2." (PMID 32998722, 2020). "It has been demonstrated in numerous cancers that there is cell-to-cell variation in the expression of SOX2, even in the same tumor." (PMID 32457900, 2020). "SOX2 expression is critical for tumor initiation and growth, and regulates self-renewal and long-term growth of CSCs." (PMID 32850316, 2020).
tumor (continued). "Collectively, our findings demonstrate that elevating SOX2 in vivo leads to a reversible state of tumor growth arrest in four different tumor cell lines representing three different tumor types." (PMID 32998722, 2020). "Analyses of in vivo orthotopic tumor also indicated that 100% of SOX2+ or Nestin+ GSLCs were BPA+, whereas only 36.9% of glial fibrillary acidic protein (GFAP)+ DCs were BPA+." (PMID 33086625, 2020). "Western blot analysis and RT-qPCR analyses were used to detect the mRNA and protein expression of tumor stem cell markers (Sox-2, Oct-4, Nanog, Aldh1 and Slug)." (PMID 32351328, 2020). "In order to further confirm SOX2 was up‐regulated by NF‐YA, the SOX2 protein in SiHa cells overexpressed NF‐YA was silenced, and xenograft assay showed that the tumour formation ability was inhibited." (PMID 32954681, 2020). "Altogether, it is evident that elevating SOX2 above levels required for proliferation leads to reduction in proliferation of both normal cells and tumor cells." (PMID 32998722, 2020). "Sox2 was totally absent from the normal mammary gland, as reported in humans, but most of the FMCs analyzed harbored Sox2-positive tumor cells." (PMID 33553286, 2020). "Transcription factors involved in embryonic stem cell (ESC) and induced pluripotent stem cell (iPSC) signaling, such as SOX2, OCT4, MYC, and KLF4, have been linked to tumor progression in various cancers." (PMID 32427884, 2020). "As sphere formation reflects the self-renewal capacity of tumor cells, we analyzed stemness marker genes, SOX2, OCT4, NANOG, and c-MYC." (PMID 33276627, 2020). "We found that long-term exposure of ERα-positive breast cancer cells to the cocktail of CAF-secreted factors strongly increased Sox2 expression involving tumor-related proteins and signaling pathways." (PMID 33228022, 2020). "These literature reviews shed light on prognostication of SOX2 as a marker and key driver for tumor aggressiveness in contexts of drug resistance and clinical relapse in addition to cancer stemness." (PMID 30517668, 2020). "This relieves the inhibitory effect of VDR on the SOX2 promoter, thereby promoting SOX2 expression and leading to tumor growth and drug resistance." (PMID 32900990, 2020). "Striking differences were uncovered regarding the clinical impact of NANOG and SOX2 expression on patient outcome, with distinct prognostic relevance depending on tumor site and lymph node infiltration." (PMID 32635524, 2020). "The studies described in this report, in addition to our earlier work, demonstrate that elevating SOX2 in vitro inhibits the proliferation of a large number of human tumor cell types." (PMID 32998722, 2020). "In line with our results, It was found that immunohistochemical expression of SOX2 was more frequently over-expressed in HCC tissue compared to non-tumor tissue." (PMID 33112555, 2020). "Specifically, SOX2 levels in tumor cells are optimized to promote tumor growth: knocking down or elevating SOX2 inhibits proliferation." (PMID 32998722, 2020). "Significantly, our current work also describes a new model in which tumor growth can be halted and restarted by first increasing then decreasing the levels of SOX2." (PMID 32998722, 2020). "SOX2 has been recently related to the acquisition of an aggressive oxidative tumor phenotype endowed with enhanced drug resistance and metastatic ability." (PMID 33203881, 2020). "Immunofluorescence (IF) staining demonstrated an OCT4+/SOX2+/KLF4+/c-MYC+ CSC subpopulation within the tumor nests (TNs) and another within the peritumoral stroma (PTS) of HNmMM tissues." (PMID 32019273, 2020). "The expression levels of these proteins were maintained in the tumor tissues over the passages in vivo, except for minor changes in SOX2 and CD133 expression." (PMID 31941033, 2020). "For examples, a small molecular inhibitor of LSD1 (CBB1007) significantly reduced SOX2 expression and suppressed growth of tumor cells." (PMID 31748974, 2020).
tumor (continued). "In this study, the tumour spheres derived from parental A549 cells overexpressed stemness‐associated markers including CD133, Nanog, Sox2 and ALDH1, which are associated with the lung CSC phenotype." (PMID 32396269, 2020). "For example, DU145 cells express substantially higher levels of endogenous SOX2 than LNCaP cells, yet the proliferation of both tumor cell lines is inhibited when SOX2 is overexpressed from an inducible promoter." (PMID 32998722, 2020). "It is interesting to note that we also observed a correlation between TP63 and SOX2 expression in single cell RNA-seq analysis of tumor ductal cells from PDA patent samples." (PMID 32329713, 2020). "Accumulated lines of evidence strongly indicate that SOX2 plays a tumor promoting role in human cancers." (PMID 32728033, 2020). "Our data indicated a new paradigm in which tumor immunogenicity was regulated through SOX2 in tumor cells, leading to possible implications for targeting SOX2 in cancer immunotherapy." (PMID 33158915, 2020). "We show that SOX2 elevation with the aid of an inducible promoter inhibits the proliferation of four tumor cell lines." (PMID 32998722, 2020). "It has also been shown that HA is involved in the maintenance of cancer stem cells (CSCs): in the presence of HA, tumor cells express stem-like markers, such as Oct4, Sox2, NANOG, and also ATP-binding cassette transporters." (PMID 33375053, 2020). "Although our studies and the work of others indicate that elevating SOX2 can lead to growth inhibition, many studies, including our own, have shown that SOX2 is required for the proliferation of tumor cells." (PMID 32998722, 2020). "We have determined that elevating SOX2 inhibits the proliferation of tumor cells that express widely different levels of endogenous SOX2." (PMID 32998722, 2020). "The aim of this study was to determine if high tumor SOX2 expression is a prognostic marker and/or predicts survival benefit from chemotherapy in stage II–III CRC." (PMID 32365581, 2020). "With the exception of tumor 2, all tumor samples showed characteristic mutations of HNSCC including amplification of 3q26.2 (TP63, SOX2, PIK3CA), 5q14.3 (APC), 8q24.3 (PTK2), 8q22.3 (LRP12) as well as loss and/or LOH of 9p21.3 (CDKN2A)." (PMID 32426287, 2020). "Second, how does elevating SOX2 inhibit the growth of tumor cells; specifically, how does elevation of SOX2 influence the expression of the cell cycle machinery?" (PMID 32998722, 2020). "Specifically, we demonstrate for the first time that elevating SOX2 in vivo leads to a reversible state of tumor growth arrest." (PMID 32998722, 2020). "The effects of DHA, cisplatin and the combination of cisplatin and DHA on Shh signaling was confirmed by testing the expression levels of nuclear Gli1, PTCH1, and Sox2 in tumor cells obtained from xenografts." (PMID 33363149, 2020). "The pro-oncogenic role of KLF4 has been demonstrated in MM cell lines, while the tumor initiation and maintenance role of SOX2 has also been well-documented." (PMID 32019273, 2020). "We have previously demonstrated that the small specific molecule CBP/β-catenin antagonist ICG-001 can inhibit the migration and growth of CSC-enriched NPC tumor spheres via the miRNA-145/SOX2 (SRY-Box Transcription Factor 2) axis and miR-150/CD44 axis." (PMID 32752071, 2020). "To confirm increased stem cell gene expression in these hyperplastic regions, we also assessed the mRNA level of Lin28B, CD34, Lgr6, and Sox2, which can serve as markers for stem-like tumor cells in skin squamous cell carcinoma." (PMID 32895364, 2020). "Key oncogenes showed differing expression profiles depending on which region of the tumor was analyzed, with lower expression of SOX2 or elevated expression of SERPINE1 and MMP19 in 5-ALA/FACS-positive cells, for example." (PMID 32904996, 2020).
tumor (continued). "High magnifications revealed that ASCL1, OLIG2, and SOX2 are also expressed specifically within the YFP+ tumor cells, which are highly irregular in shape, morphology, and density compared to normal YFP+ cells on the nontumor side (not shown)." (PMID 32573857, 2020). "We also found important differences in the prognostic significance of NANOG and SOX2 expression, depending on the tumor site." (PMID 32635524, 2020). "In this study, decreased mRNA expression of SOX2 was detected in LK1108 tumor cells sorted from co-culture of tumor cells and CAFs as spheroids when compared to tumor cells grown in spheroids alone." (PMID 33353547, 2020). "Researchers also found that SOX2 expression was frequently over-expressed in dysplasia and HCV-associated HCC tissues, compared to non-tumor tissues." (PMID 32121397, 2020). "SOX2 expression increased remarkably from ~20% in pre-malignant PanIN3 lesions to nearly 60% of poorly differentiated PDAC during course of tumor progression." (PMID 30517668, 2020). "Consistent with the previous results, knockdown of SOX2 in the acidic tumor microenvironment weakened the self-renewal ability of CRC stem cells and strengthened the sensitivity of the cells to oxaliplatin." (PMID 32900990, 2020). "A novel finding was that patients received adjuvant chemotherapy/radiotherapy usually had decreased SOX2 expression in the recurrent tumor." (PMID 31718604, 2019). "Both Klf4 overexpressing mice and p120 catenin knockout have robust NFκB activation that is an early event, and in Sox2 knockout mice, tumor progression correlates with inflammation." (PMID 30998758, 2019). "Targeting oncogenic beta-catenin in SOX2+ PSCs in the mouse generates clusters of senescent SOX2+ cells that induce tumours resembling ACP in a paracrine manner, that is the tumours do not derive from the targeted SOX2+ PSCs." (PMID 30912742, 2019). "Accordingly, various studies using large cohorts of HNSCC samples have demonstrated that SOX2 expression significantly correlated with tumor recurrence and poor prognosis." (PMID 30823625, 2019). "In the preclinical model in which pancreatic CSCs were subcutaneously implanted into nude mice, brexpiprazole suppressed tumor growth, in addition to reducing the expression of Sox2, a marker for CSCs, and survivin." (PMID 31191825, 2019). "More importantly, experimental findings derived from limiting dilution and tumorigenic assay in vivo further revealed the pivotal roles of TAZ and SOX2 required for HNSCC tumor initiation and overgrowth." (PMID 31399556, 2019). "(E) Lineage tracing of SOX2+ cells in Sox2CreERT2/+;Lats1fl/fl;Lats2fl/+R26mTmG/+ reveals that tumour regions accumulating YAP as seen by immunofluorescence, are composed of GFP+ cells at P35." (PMID 30912742, 2019). "Disruption of C3aR expression dampened tumour growth and the expression of Wnt‐1, β‐catenin and Sox‐2 in the xenograft model." (PMID 30825266, 2019). "To analyze the effect of a SOX2-/FOXA2-deficiency on TCam-2 cells in vivo, we xenografted TCam-2-ΔSOX2 and TCam-2-ΔSOX2/FOXA2 cells into the flank of nude mice and analyzed the tumor tissues after six and twelve weeks." (PMID 31130628, 2019). "These murine tumors were composed predominantly of SOX2+ cells, suggesting that loss of LATS, obtained by genetic manipulation, drives deregulation of SOX2+ pituitary stem cells, leading to tumor formation." (PMID 31708878, 2019). "Five days after irradiation, tumors were explanted and tumor sections stained for Sox2 and Klf4 and subjected to an automated image analysis." (PMID 30700319, 2019). "The results revealed that the protein expression levels of NANOG, OCT4, and SOX2 were significantly higher in tumour spheres than in their parental cells." (PMID 31889900, 2019). "Recent studies demonstrated that SOX2-expressing cells are the founding CSC population driving tumor initiation and therapy resistance." (PMID 31844113, 2019).
tumor (continued). "Each individual tumor specimen is represented by a single bar, with red bars indicating patients with CNGs in SOX2 or ST6GAL1." (PMID 31610800, 2019). "Tumour regions were mostly composed of SOX2 positive cells, a sub-population of which also expressed SOX9 (85–97% of cells, 7 tumours across four pituitaries)." (PMID 30912742, 2019). "There was a significant inverse correlation between the expression of SOX2 and podoplanin with the tumor grade (p=0.002 and p=0.017, respectively)." (PMID 31508790, 2019). "OCT4 and SOX2 were found expressed significantly higher in 9/10 and 7/10 tumor samples, respectively." (PMID 31885625, 2019). "In our previous study, we demonstrated that the number of tumor cells positive for SOX2 or CD166 in the bone micro-E were significantly higher than those in the subQ micro-E, and we confirmed the evidence in this study." (PMID 31619018, 2019). "While Sox2+ cells were insensitive to Hh pathway inhibition, they displayed Wnt pathway activation, and modulation of Wnt signaling regulated their tumor-propagating abilities." (PMID 31700613, 2019). "Mouse skin SCC cells expressing CD34 and α6-integrin, or Sox2 are enriched in tumor-initiating or cancer stem-like cells (CSCs) relative to the bulk of tumor cells." (PMID 30874597, 2019). "The expression of SOX2 at the site of lymph node metastasis compared to primary tumor site has been investigated in other malignancies." (PMID 31244283, 2019). "This construct allows us to selectively eliminate SORE6+-CSCs in the bulk of tumors and provides compelling evidence that SOX2/OCT4 overexpression in prostate CSCs contributes to tumor initiation, progression, and tumor relapse from chemotherapy." (PMID 31500347, 2019). "The tumor-promoting activity and involvement of SOX2 in tumor progression has been extensively demonstrated, thereby emerging as a promising therapeutic target." (PMID 30823625, 2019). "Nuclear SOX2 expression was also found in 49 (39%) OSCC cases, was more frequent in early tumor stages and N0 cases, and was associated with a better survival." (PMID 31640140, 2019). "The expression of SOX2 correlated positively with the stage of the tumor (p=0.029) and inversely with the grade of the tumor (p=0.002)." (PMID 31508790, 2019). "Further analysis of the stemness-associated markers in above tumor tissues showed that the expression levels of ALDH1, CD49f, Sox2, Nanog, and Oct4 were also higher in HeLa cells derived CSCs-derived tumor tissues compared to HeLa cells-derived tumor tissues." (PMID 30791957, 2019). "When stable SOX2-knockdown cells by shRNA lentiviral constructs were selected and transplanted subcutaneously with diverse amounts of cells, much lower incidence of tumor formation was observed in SOX2-depleted cells." (PMID 31399556, 2019). "Taken together, these results indicate the importance of the SOX2 molecule and SOX2+ cells in tumor development." (PMID 31041783, 2019). "Xenograft studies using stable and inducible knockdown of Sox2 showed a reduction in the growth of tumours, which highlights the critical role of SOX2 in the development and maintenance of SCC." (PMID 31060263, 2019). "Since GCV is toxic for replicating cells, these observations strongly suggest the existence in vitro of a CD133+ and OCT4/SOX2+ pool of GCV surviving tumor stem cells." (PMID 31267022, 2019). "Positive SOX2 staining was found in 49 (39%) cases located in the nucleus of tumor cells, whereas stromal cells and normal epithelium showed negligible expression." (PMID 31640140, 2019). "There is mounting evidence demonstrating the role of SOX2 in tumorigenesis, and its contribution to tumor progression has been extensively documented in multiple cancers." (PMID 30823625, 2019).